CASP4 (caspase 4)
Diseases named in the same sentence as CASP4 in open-access papers (continued):
Sharing a sentence is not in itself a finding about the gene and the disease.
glioma (continued). "The specificity of the correlation between CASP4 expression and outcomes in different tumors indicates the potential for synergistic effects with radiotherapy, chemotherapy and immunotherapy in gliomas." (PMID 39075190, 2024). "Given the potential role of CASP4 in driving glioma progression, we analyzed the relationship between CASP4 expression and glioma chemotherapy treatment using the GDSC database." (PMID 39075190, 2024). "We then used comprehensive analysis and multiple visualization methods to explore the mechanisms by which CASP4 affects the outcomes of glioma therapy." (PMID 39075190, 2024). "The correlation between the upregulation of CASP4 expression levels and poor prognosis of glioma patients was the most significant compared to changes in the other pivotal pyroptosis-related genes." (PMID 39075190, 2024). "To confirm the expression of CASP4 at the cancer cell and tissue level, we collected glioma cells and histopathological sections from patients." (PMID 39075190, 2024). "Based on the critical role of immune scores and steps in glioma treatment, our study identified a strong correlation between CASP4 expression and ESTIMATE scores and immune steps in glioma patients." (PMID 39075190, 2024). "We conducted a series of studies, including analyses of clinical survival prognosis, functional enrichment, and patient staging, to determine the role of CASP4 in gliomas." (PMID 39075190, 2024). "We also used the ESTIMATE, immunity, and stroma scores to assess the links between CASP4 and the glioma immune microenvironment." (PMID 39075190, 2024). "CASP4 is a predictive therapeutic target that is closely related to immunotherapy and resistance to chemotherapeutic agents in gliomas." (PMID 39075190, 2024). "Investigating the role of CASP4 in influencing these steps has the potential to improve the efficacy of immunotherapy for glioma, making CASP4 an important predictor of accurate glioma treatment outcomes." (PMID 39075190, 2024). "The gene expression profiles of all glioma samples and paired normal tissues showed that CASP4 was overexpressed in gliomas." (PMID 39075190, 2024). "For this reason, we investigated the correlation between CASP4 and chemotherapeutic drug sensitivity with the aim of providing possible targets for improving the efficacy of chemotherapy in glioma patients." (PMID 39075190, 2024). "As CASP4 interactions among chemokines or chemokine receptors can affect immunotherapy and the migration of immune cells in gliomas, we used PPI network analysis to better understand the interactions." (PMID 39075190, 2024). "In accordance with the results from TCGA data, our analysis showed that CASP4 expression was elevated in glioma cells compared with normal astrocytes, and CASP4 was highly expressed in gliomas compared with normal paracancerous tissues." (PMID 39075190, 2024). "To further validate the effect of CASP4 on glioma cells, we inhibited CASP4 expression in U251 glioma cells and verified the inhibition efficiency by Western blot." (PMID 39075190, 2024). "Of particular relevance, we found that CASP4 has an important effect on tumor-infiltrating immune cells in gliomas." (PMID 39075190, 2024). "In relation to the poor outcomes of immunotherapy and drug therapy in glioma patients, we found that glioma CASP4 expression correlated with the degree of infiltration of multiple immune cell types and sensitivity to chemotherapeutic agents." (PMID 39075190, 2024). "TCGA and the Chinese Glioma Genome Atlas (CGGA) databases showed that reduced CASP4 expression leads to the potent clinical deterioration of glioma patients." (PMID 39075190, 2024). "Through integrated bioinformatics analysis techniques and evaluation of the prognostic significance of pivotal pyroptosis genes, we identified CASP4 as a gene that is critical to glioma pyroptosis." (PMID 39075190, 2024).
glioma (continued). "Based on our study, we propose that the important pyroptosis gene CASP4 can be used to predict the sensitivity of glioma cells to paclitaxel and sunitinib." (PMID 39075190, 2024). "We first analyzed the relationship between CASP4 expression and glioma cell pyroptosis as a recently discovered form of cell death." (PMID 39075190, 2024). "These pathways affect tumor immunotherapy, drug therapy, and patient prognosis in gliomas, and CASP4 has demonstrated its potential as a prognostic predictor and therapeutic target." (PMID 39075190, 2024). "Previous studies have demonstrated that higher expression of CASP4 can serve as a prognostic marker in glioma and renal cell carcinoma." (PMID 37245006, 2023). "This study found that, compared with normal tissues, glioma tissues have a significantly higher CASP4 expression at both the mRNA and protein levels." (PMID 36713560, 2022). "CASP4 in gliomas can promote tumor cells to release irritant factors and enrich microglia in tumor tissues." (PMID 36713560, 2022). "The present study demonstrated that CASP4 participated in the regulation of immune infiltration in the local microenvironment of gliomas." (PMID 36713560, 2022). "The differential gene analysis in the current study showed that CASP4 expression is associated with several other important molecules of pyroptosis, including GSDMD, CASP1, IL-18, and TLR2, in gliomas." (PMID 36713560, 2022). "TCGA analysis of the relationship between CASP4 expression and glioma survival suggested that a high CASP4 expression was related to poor OS, and the same result was observed in gliomas of different grades." (PMID 36713560, 2022). "We combined all tumor expression data from TCGA with GEPIA2 data and obtained differentially expressed genes that were correlated with CASP4 expression in gliomas, including GSDMD, CASP1, IL-18, and TLR2." (PMID 36713560, 2022). "We used expression data from The Cancer Genome Atlas and the Chinese Glioma Genome Atlas to explore the relationship between CASP4 expression and glioma prognosis." (PMID 36713560, 2022). "The differential expression of CASP4 in gliomas and normal tissues was fifirst tested, and then the connection between CASP4 and tumor prognosis was explored." (PMID 36713560, 2022). "Overall, the results support that CASP4 participates in glioma prognosis by activating immune cells." (PMID 36713560, 2022). "CASP4 expression influenced several factors in gliomas, including clinicopathological variables, tumor microenvironment, immune cell pathway, tumor immune infiltration, and PPI." (PMID 36713560, 2022). "Previously, a prognostic model comprising three PRGs (CASP4, CASP9, and NOD2 (encoding nucleotide binding oligomerization domain containing 2)) was constructed to predict the outcomes of patients with glioma." (PMID 36119521, 2022). "Towards this goal, bioinformatic methods were used to determine the potential role of CASP4 in gliomas." (PMID 36713560, 2022). "In terms of mechanism, the risk-score signature was positively associated with the expression of inflammatory molecules such as S100A11 and CASP4 in glioma." (PMID 35118063, 2021). "To the best of our knowledge, the current literature on the role of CASP4 in glioma immunotherapy and chemotherapy is superficial and limited in scope; therefore, we chose to conduct an in-depth and comprehensive analysis of the role of CASP4 in the treatment of glioma." (PMID 39075190, 2024). "Finally, analysis at the cellular and tissue levels indicated an increase in CASP4 expression in glioma, and that CASP4 inhibition significantly inhibited the proliferation of glioma cells." (PMID 39075190, 2024). "Computational analysis of the effect of CASP4 on the infiltration level and recruitment of glioma immune cells revealed that CASP4 expression was closely associated with a series of tumor-suppressive immune checkpoint molecules, chemokines, and chemokine receptors." (PMID 39075190, 2024).
glioma (continued). "Finally, we verified the aberrant expression of CASP4 by in vitro analysis of cells and histological samples from glioma patients." (PMID 39075190, 2024). "CASP4 may guide the development of different types of gliomas, and it is expected to make an important contribution to the prediction of glioma typing and the development of individualized treatments." (PMID 39075190, 2024). "Considering the important role of chemokines in immune cell migration, we further explored whether the role of CASP4 in the immune microenvironment of gliomas is related to this type of regulatory factors." (PMID 39075190, 2024). "This implied that CASP4 may be involved in immune cell migration in gliomas by regulating IL-1β protein expression." (PMID 39075190, 2024). "CASP4 expression was related to the clinicopathological features and prognosis of glioma patients." (PMID 36713560, 2022). "This study aimed to explore the mechanism of CASP4 in gliomas." (PMID 36713560, 2022). "Univariate Cox regression analysis showed that CASP4 may be an independent factor affecting the prognosis of patients with glioma." (PMID 36713560, 2022). "This study aimed to prove that CASP4 has a key role in the mechanism of gliomas." (PMID 36713560, 2022). "In the time-dependent ROC curves to evaluate the usefulness of CASP4 expression for distinguishing between glioma and normal tissues, the area under the curve values for predicting the 1-, 3-, and 5-year survival rates were 0.856, 0.867, and 0.798, respectively." (PMID 36713560, 2022). "Genes, such as OAS2, ULBP1, HERPUD1, and CASP4, are diagnosed with the growth of various cancers, such as oral cancer, cervical cancer, and gliomas, but these genes may identify with the development of BRCA." (PMID 31311202, 2019). "Furthermore, we showed that CASP4 expression affected glioma cell proliferation." (PMID 39075190, 2024). "Moreover, we experimentally validated the function of CASP4 at the glioma cell and tissue levels." (PMID 39075190, 2024). "Although some reports have addressed the role of CASP4 in gliomas, to the best of our knowledge, the mechanisms underlying the role of CASP4 in immunotherapy and chemotherapy have not been fully elucidated; therefore, we selected CASP4 for further analysis." (PMID 39075190, 2024). "The data showed that high CASP4 expression is strongly correlated with the degree of migration and recruitment of immune cells to the tumor (Step 4), thus affecting the anticancer immune status and the proportion of tumor-infiltrating immune cells in glioma patients." (PMID 39075190, 2024). "Moreover, Cox regression analysis indicated that CASP4 expression was independently associated with tumor grade, age, histological type, 1p/19q co-deletion, IDH status, and primary treatment outcomes, indicating that it is related to glioma progression." (PMID 36713560, 2022). "Therefore, a high CASP4 expression indicates poor prognosis in glioma patients." (PMID 36713560, 2022). "Collectively, these findings indicated that CASP4 may be a prognostic indicator for gliomas." (PMID 36713560, 2022). "Using the online database GEPIA2, we found that the correlation between CASP4 expression levels and poor glioma prognosis (OS and DFS) was the most significant, suggesting that CASP4 plays a critical role in the prognosis of glioma treatment." (PMID 39075190, 2024). "Therefore, dendritic cells, although closely associated with CASP4 expression, may not be the main reason why CASP4 affects immunotherapy in gliomas." (PMID 39075190, 2024). "To further explore the molecular regulatory mechanism of CASP4 in gliomas, we used TCGA data for the GO and KEGG analysis of the CASP4-coexpressed genes and the GSEA analysis of CASP4." (PMID 36713560, 2022). "Compared with HA 1800 and HMC3 cell lines, the expression levels of CASP4, CASP9 and GSDMC showed an overall upward trend, and the IL1A level showed an overall downward trend in glioma cell lines." (PMID 35547808, 2022).
glioma (continued). "The authors found that the increased expression of PANoptosis genes ZBP1, ADAR, CASP2, CASP3, CASP4, CASP8, and GSDMD is detrimental in low-grade glioma across multiple survival models, while AIM2, CASP3, CASP4, and TNFRSF10 also negatively influenced kidney renal cell carcinoma." (PMID 38169587, 2024). "We also analyzed the correlation between CASP4 expression and glioma immune cell infiltration using The Tumor Immuno Estimation Resource (TIMER) database to explore the potential function of CASP4 in glioma chemotherapy and immunotherapy." (PMID 39075190, 2024). "Finally, combined with Multivariate Cox regression analyses, four PRGs (CASP4, CASP9, GSDMC, IL1A) were identified as prognostic biomarkers for glioma patients." (PMID 35547808, 2022). "In addition, we explored the proteins express by CASP4, CASP9, and GSDMC in glioma patients through the Human Protein Atlas database, and CASP4, CASP9 exhibited higher staining intensity in glioma than normal brain tissues." (PMID 35547808, 2022). "Based on a previous database search and some experiments, we can conclude that non-classical pyroptosis mediated by CASP4 plays a vital role in the occurrence and development of glioma." (PMID 36713560, 2022). "Our study showed that CASP4 was negatively correlated with OS and positively correlated with the WHO grade of glioma patients, suggesting that CASP4 may act as an oncogene in glioma." (PMID 35547808, 2022). "CASP4-mediated non-classical pyroptosis plays an important role in gliomas." (PMID 36713560, 2022). "Whether CASP4 (Caspase-4) and S100A11 act synergistically in gliomas remains unclear." (PMID 35118063, 2021). "Furthermore, the expression levels of genes encoding NLR proteins (NLRP12, NOD2, NOD1, NLRC4, and NAIP), inflammasome adaptor molecules (PYCARD), and proinflammatory caspases (CASP1, CASP4, and CASP5) were significantly higher in glioma patients than in normal controls." (PMID 31133717, 2019). "However, the roles of CASP4 and CASP5 in gliomas has not been reported." (PMID 36861130, 2023).
melanoma (13 papers, 2012 to 2024). A malignant, usually aggressive tumor composed of atypical, neoplastic melanocytes. "Caspase-4 is closely linked to the endoplasmic reticulum (ER) stress response, particularly in melanoma cells." (PMID 39329914, 2024). "-They contribute to TRAIL-induced apoptosis and are associated with the induction of ER stress by TRAIL in melanoma cells.-Caspase-3 inhibition blocks caspase-4 activation, while caspase-4 inhibition attenuates TRAIL-induced caspase-3 activation." (PMID 39329914, 2024). "CASP4, an inflammatory caspase, has previously been associated with Apo2L/TRAIL sensitivity in melanoma and rheumatoid arthritis synovial fibroblasts, but otherwise is not widely associated with DR5 signaling and thus was an unexpected finding." (PMID 26378449, 2015). "Importantly, TRAIL-induced ER stress, evidenced by specific stress markers, is necessary for caspase-4 activation, further solidifying the link between ER stress and apoptosis in melanoma." (PMID 39329914, 2024). "Interestingly, 3 of pyroptosis-associated genes including CASP1, CASP4 and PYCARD, can predict the effectiveness of anti-PD-1 immunotherapy for patients with melanoma." (PMID 36068291, 2022). "Caspase-4 was recently shown to be involved in TRAIL-induced apoptosis of human melanoma cells." (PMID 22613960, 2012). "In particular, the levels of the circulating caspase-4 were significantly lower in the plasma of endometrial carcinoma (KE, n = 12), ovarian carcinoma (KO, n = 12), colon carcinoma (K colon, n = 16), liver carcinoma (K liver, n = 5), bladder carcinoma (K bladder, n = 6) and melanoma (n = 9)." (PMID 29721208, 2018). "Here, we found that δ-TT induced the cleavage of caspase-4 in both BLM and A375 melanoma cell lines." (PMID 27461002, 2016). "In melanoma cells, δ-TT exerted its antitumor effect through activation of the PERK/p-eIF2α/ATF4/CHOP, IRE1α and caspase-4 ER stress-related branches." (PMID 27461002, 2016). "Their study identified three pyroptosis-related genes—CASP1, CASP4, and PYCARD—that could predict the efficacy of anti-PD-1 immunotherapy in melanoma." (PMID 39329914, 2024). "In our bioinformatics and experiment data proved that CASP4 and PYCARD might act as potential biomarkers to predict the effectiveness of anti-PD-1 immunotherapy for melanoma patients." (PMID 36068291, 2022). "NLRP1 (NLR family pyrin domain containing 1), confirmed as a proinflammatory protein in melanoma progression, was downregulated significantly by CP, as were the NLRP1-related caspase activation and recruitment domains (CARD) proteins, including caspase-1 and caspase-4." (PMID 30149677, 2018). "Furthermore, Treg from melanoma, Treg from TC-1 tumor, Treg from breast tumor, Treg from B16 tumor, Treg from MC38 tumor, and Treg from CT26 tumor upregulated 2, 18, 9, 42, 27, and 9 caspase-1 secretomic genes, and 8, 33, 16, 72, 39, and 11 caspase-4 secretomic genes, respectively." (PMID 34084175, 2021). "For example, CASP4, NLRP1, MEFV, IL18, and NINJ1 correlated positively with GSDMD in metastatic melanoma patients but not in primary melanoma patients." (PMID 38229080, 2024). "However, some studies suggest that SARS-CoV-2 infection is associated with other inflammasomes as well; such as NLRP1, absent in melanoma-2 (AIM-2), caspase-4 and -8 which were mostly found during dsRNA virus or bacteria infection." (PMID 37360532, 2023).
breast carcinoma (12 papers, 2009 to 2025). "After treatment with SWCNT–COOH–CDDP complex, caspase-4 was activated in both 2D and 3D breast cancer cultures, which can highlight the initiation of ER stress-induced apoptosis." (PMID 38739308, 2024). "Instead, SWCNT–COOH–CDDP complex induced the overexpression of caspase-4 compared to control in both breast cancer 2D and 3D cultures." (PMID 38739308, 2024). "Similar conclusions were drawn by Zhu and Li (2018), who concluded that abnormal methylation levels of the promoter region of CASP4 are related to the occurrence and development of breast cancer." (PMID 33584797, 2020). "Caspase-4 expression was lowest in breast cancer cell lines compared to in other cell types tested." (PMID 29245990, 2017). "Studies have shown that timosaponin AIII can induce the apoptosis of a variety of tumor cells, such as breast cancer and colorectal cancer cells, by activating the ATM/Chk2 and p38 MAPK signaling pathways, inducing autophagy, activating Caspase-4/9, and blocking the cell cycle." (PMID 34202717, 2021). "We previously demonstrated that the factors secreted by hUCMSCs induced pyroptosis in the breast cancer cell line MCF7.Furthermore, RNA sequencing studies revealed a significant increase in the expression of pyroptosis-related genes CASP4 and NLRP1 in pyroptotic MCF7cells." (PMID 32695183, 2020). "Furthermore, an association with various estrogen-dependent genes such as ANXA1, PIWIL2, CASP4, ESR1/ESR2, PLAC1, and SOCS2, has been shown in breast cancer—however, up to date, no such data concerning adenocarcinomas of the esophagogastric junction have been published." (PMID 31467538, 2019).